GPR4 (G protein-coupled receptor 4)
Diseases named in the same sentence as GPR4 in open-access papers (continued):
Sharing a sentence is not in itself a finding about the gene and the disease.
GPR4 also shares sentences with these, for which no sentence is quoted: chronic obstructive pulmonary disease (2 papers); diabetes (2); Hypertension (2); adenocarcinoma (1); basal cell carcinoma (1); brain hemorrhage (1); cerebral infarction (1); Chronic colitis (1); colon dysplasia (1); fibrosis (1); hepatocellular carcinoma (1); kidney cancer (1); Lewis lung carcinoma (1); liver cancer (1); multiple sclerosis (1); Obesity (1); squamous cell carcinoma (1); ulcerative colitis (1); viral diseases (1).